NID2 (nidogen 2)
Diseases named in the same sentence as NID2 in open-access papers (continued):
Sharing a sentence is not in itself a finding about the gene and the disease.
cancer (continued). "Detection of NID2 methylation was proposed as a biomarker for the diagnosis of many cancers including non-small cell carcinoma of lung, urothelial carcinoma of urinary bladder and squamous cell carcinoma of oral cavity." (PMID 27793011, 2016). "Immunohistochemical (IHC) analysis of NID2 was used to show protein expression levels directly in cancer tissues." (PMID 27793011, 2016). "This study provides novel insights into the crucial tumor metastasis suppression roles of NID2 in cancers." (PMID 27793011, 2016). "Results suggested that NID2 re-expression was unable to induce significant changes in both the in vitro cell proliferation and in vivo tumorigenicity of the cancer cells." (PMID 27793011, 2016). "In both NPC and ESCC, the CpG-rich promoter regions of NID2 were hypermethylated, when compared to the matched non-cancer tissues." (PMID 27793011, 2016). "We found that 74% of 50 NPC biopsies had a methylated NID2 promoter, while the majority of the adjacent non-cancer tissues remained unmethylated (66%)." (PMID 27793011, 2016). "We show that CpG islands of both NID1 and NID2 genes are aberrantly methylated in human cancer samples and cancer cell lines." (PMID 17328794, 2007). "We evaluated the distribution of NID2 expression levels for pan-cancer in TCGA." (PMID 40332526, 2025). "Another aspect worth discussing is the role of nidogen-2 in cancer metastasis." (PMID 41181108, 2025). "Given that our NID2-reduced matrices were softer than control, these invasion data are in line with previous work demonstrating that a softer microenvironment can result in a less invasive phenotype in cancer cells." (PMID 38959305, 2024). "Our orthotopic coinjection experiments with control or NID2 knockdown CAFs with cancer cells reveal that NID2 targeting can reduce primary tumor growth (with chemotherapy treatment) and reduce metastatic burden in the liver, leading to improvements in median survival." (PMID 38959305, 2024). "Further investigation using microarray analysis and other techniques revealed that NID2 was hypermethylated, while its demethylation or overexpression could decrease many signs of cancer, such as proliferation, migration, invasion, including apoptosis." (PMID 32171289, 2020). "Furthermore, NID2 also plays a significant role in impairing the migration and invasion abilities of the cancer cells." (PMID 27793011, 2016). "The Human Phospho-Kinase Antibody Array was utilized to explore the possible cancer signaling pathways that may be affected by NID2." (PMID 27793011, 2016). "NID2 was also consistently found to be hypermethylated in several other cancers." (PMID 27793011, 2016). "NID2 re-expression in cancer cells revealed attenuated EGFR activity." (PMID 27793011, 2016). "NID2 silencing was reported in many cancer types and the aberrant promoter hypermethylation is one of the most critical events detected in different malignancies, including gastric, bladder, and invasive cervical cancers." (PMID 27793011, 2016). "Thus, the down-regulation of NID2 by promoter hypermethylation appears to be a key event leading to cancer metastasis." (PMID 27793011, 2016). "Despite the substantial number of studies associating NID2 to different cancers, to the best of our knowledge, there have not been any in-depth functional studies to elucidate the potential suppressive role of NID2 in cancers, especially in NPC and ESCC." (PMID 27793011, 2016). "Hence, in the present study, we aimed to scrutinize the functional role of NID2 in these cancers." (PMID 27793011, 2016). "To do this, we coinjected a 1:3 ratio of luciferase-expressing KPC cancer cells and CAFs (GFP KRAB or B500 NID2 KRAB) into the pancreas of NOD.Cg-PrkdcscidIL2rgtm1Wjl/SzAusb (NSG) mice, as previously achieved." (PMID 38959305, 2024). "Results showed that promoter methylation of NID2 was significantly higher in NPC and ESCC samples than in their adjacent non-cancer counterparts." (PMID 27793011, 2016).
cancer (continued). "The expression levels of NID2 were determined in paired NPC/ESCC and non-cancer biopsies to validate their clinical relevance." (PMID 27793011, 2016). "As NID2 harbors several de novo methylated loci in the CpG islands, it is a potential TSG/MSG in these cancers." (PMID 27793011, 2016). "Using biomechanical assessments, second harmonic generation imaging, and birefringence analysis, we show that NID2 reduction by CRISPR interference (CRISPRi) in CAFs reduces stiffness and matrix remodeling in three-dimensional models, leading to impaired cancer cell invasion." (PMID 38959305, 2024). "NID2 is a ubiquitous component in the ECM and plays a vital role in cancer development." (PMID 36106120, 2022). "Among the genes that showed differential methylation, NID2 was one of the top candidate genes showing significant differences in the methylation levels between cancer and non-cancer specimens." (PMID 27793011, 2016). "The observed down-regulation of several extracellular matrix and basement membrane proteins, such as COL18A1 and NID2, could have great consequences on the integrity of the tissue and lead to altered differentiation (KRT4) and cancer-like alterations that may explain the characteristic phenotype." (PMID 25093596, 2014). "Studies of how NID2 may be involved in different cancer signaling pathways are still lacking." (PMID 27793011, 2016).
tumor (26 papers, 2007 to 2026). "Strikingly, we observed Nidogen-2-positive cells to be tightly associated with blood vessels in early stages of tumor development (8 weeks old MMTV-PyMT mice)." (PMID 30514914, 2018). "Furthermore, we show using intravital (in vivo) imaging that NID2 reduction in CAFs causes reduced tumor fibrosis and vascular changes as well as an enhanced response to gemcitabine/Abraxane [nanoparticle albumin–bound paclitaxel (nab-paclitaxel)] chemotherapy." (PMID 38959305, 2024). "NID2 is a key component of the BM and plays an important role in ECM organization and tumor-associated microenvironmental remodeling." (PMID 41782202, 2026). "Two additional GEO datasets, GSE7696 and GSE4290, were analyzed, and substantial overexpression of NID2 in GBM was confirmed compared with the non-tumor brain tissue." (PMID 40332526, 2025). "The number of tumor cells invaded through the Matrigel-coated transwell inserts was significantly increased by NID2 overexpression in T98G and U87MG cells (lower)." (PMID 40332526, 2025). "Guided by our organotypic data, we next assessed the effects of CAF-derived NID2 on tumor growth in vivo in the context of standard-of-care gemcitabine/Abraxane (nab-paclitaxel) chemotherapy." (PMID 38959305, 2024). "That is, (i) an antimetastatic effect alone and, (ii) in the context of chemotherapy, NID2 effects on tumor vasculature likely also improve response to chemotherapy in this deadly disease." (PMID 38959305, 2024). "In this study, we stained KPC tumor tissues for NID2, CD31 (endothelial cells), and CD146 (perivascular stromal cells)." (PMID 38959305, 2024). "Nidogen-1 (NID1) was downregulated in all tumor types, while NID2 was downregulated only in SCLC, compared to adjacent tissue." (PMID 35681609, 2022). "ITGA7 and NID2 promoter regions were bisulfite sequenced in one normal sample and four tumor samples and the results confirmed MSRE-PCR findings in all cases." (PMID 33500458, 2021). "Although common tumor EC genes such as Nid2 and Col15a1, were detected in s.c. and liver tumor-derived ECs, two distinct clusters formed based on the site of tumor growth (i.e., s.c. and liver)." (PMID 32440964, 2020). "During the course of tumor progression, increasing amounts of Nidogen-2-positive cells were found detached from vessels, showing streaks of cells infiltrating the stroma of tumors from 12- and 15-weeks-old mice." (PMID 30514914, 2018). "In conclusion, NID2 plays an important role as an ECM protein defining the tumor microenvironment and is involved in metastasis suppression." (PMID 27793011, 2016). "This functional complementation study further supported the potential of the NID2 to function as a tumor suppressor or metastasis suppressor." (PMID 27793011, 2016). "On average, the number of tumor spheres (≥ 100 μm) formed in NID2-expressing HONE1 and KYSE30 was reduced to 62% and 45%, respectively, of the VA control (100%)." (PMID 27793011, 2016). "As a secretory basement membrane protein constituting the tumor microenvironment, changes in NID2 protein levels can lead to a change in the ECM signaling cascade to redefine cell fate." (PMID 27793011, 2016). "NID2 has been shown to be elevated during phorbol 12-myristate 13-acetate-induced invasion of several human tumor cell lines and as a potential tumor biomarker." (PMID 23251436, 2012). "There is a strong correlation between NID2 upregulation and tumor grade." (PMID 40332526, 2025). "On the basis of our promising data, future work could also involve developing an anti-NID2 therapy to promote normalization of the stroma and decreased tumor stiffness." (PMID 38959305, 2024). "This indicates that NID2 reduction may indirectly affect tumor vascularization, due to the reduction in tumor fibrosis observed via reduced Picrosirius Red intensity and changes in birefringence proportions observed with polarized light imaging." (PMID 38959305, 2024).
tumor (continued). "This could, in part, explain why gemcitabine/Abraxane was more effective at reducing tumor burden in the NID2-depleted tumors in this subcutaneous in vivo model." (PMID 38959305, 2024). "Indeed, Nidogen-2, a protein secreted by “vascular CAFs” in murine BC model, was firstly detected among perivascular cells but relocated within the tumor stroma at later stages of tumor progression." (PMID 33553157, 2020). "However, expression of NID2 in the TCGA OSCC dataset was higher in tumor samples compared to adjacent normal epithelia with a sustained elevated expression in tumor grades 1 to 3 (data not shown)." (PMID 27128408, 2016). "In order to eliminate the possibility that the difference in the ability for metastasis is induced by the inhibition of the in vivo tumor growth by NID2, the in vitro cell proliferation assay and in vivo subcutaneous nude mouse tumorigenicity assay were performed." (PMID 27793011, 2016). "For instance, the knockout of NID2 has been shown to suppress CAF activation, thereby inhibiting both tumor fibrosis and metastasis, while concurrently modulating tumor vasculature and enhancing therapeutic efficacy." (PMID 40948749, 2025). "Using unsupervised clustering analysis, we found that many OS-known genes were differentially upregulated (Rrp9, Rcc1, Ran), while others were downregulated (Mylk, Nid2) in the BMT and tumor cells compared to the control BM cells." (PMID 38182577, 2024). "The sensitivity of detecting Ta tumor was also superior to the reported methylation assays by DLX1 and ITGA4 (50.0–84.6%) and BCL2, CDKN2A and NID2 (61.1%)." (PMID 33902700, 2021). "Another group investigated 103 tumors and 23 normal lung tissue samples and suggested using NID2 and RASSF1A genes as LC tumor-markers." (PMID 31526458, 2019). "Moreover, the transwell migration assay also revealed that overexpression of NID2 in T98G and U87MG cells increased the number of tumor cells migrated through the membrane (upper)." (PMID 40332526, 2025). "For the ITGA4, ITGA9, NID1 and NID2 genes for which XmaI-RRBS data are available, we have calculated the relative fractions of methylated and nonmethylated alleles in tumor samples, in respect to HER2 expression in tumors." (PMID 33500458, 2021). "Furthermore, co-immunostaining for the vCAF marker Nidogen-2 and the endothelial cell marker CD31 showed that the Nidogen-2+ vCAFs were predominantly localized around the blood vessels in the early stages of tumor development, which is consistent with their gene expression profile." (PMID 33906694, 2021). "Indeed, simultaneous detection of the vCAF marker Nidogen-2, the mCAF marker PDGFRα, and the dCAF marker SCRG1, identified three distinct stromal populations with divergent growth patterns and localization in relation to the nests of tumor cells." (PMID 30514914, 2018). "However, despite the nearly complete absence of FN in the tumor, basement membrane components ColIV, laminin, Nid-1 and Nid-2 appeared to be properly assembled." (PMID 25807551, 2015). "Furthermore, analysis of nidogen-2 by immunostaining in primary tumors confirmed that only tumor samples presenting aberrant methylation lacked nidogen expression." (PMID 17328794, 2007).
neurological disease (2 papers, 2022 to 2023). "Nidogen 2 (NID2) has been discovered to cause neurological disease." (PMID 35627223, 2022). "A positive correlation between m1A modification and gene expression was observed, and we selected genes related to neurological diseases (Bag3, Csf1, Cyp1b1, Egfr, Flnc, Lox, Mt1, Nid2, Rab3b, and Tubb4a) for analysis, with MeRIP-RT-PCR and qRT-PCR performed to verify this phenomenon." (PMID 37173310, 2023).
gastrointestinal neoplasms (1 paper, 2007). "Immuno-staining for nidogen-2 confirmed the correlation between aberrant methylation and loss of nidogen expression also in primary tumors, implying that aberrant methylation was a mechanism for inhibiting nidogens expression in human gastrointestinal tumors." (PMID 17328794, 2007). "We investigated the presence of aberrant methylation at the NID1 and NID2 promoters in primary gastrointestinal neoplasms." (PMID 17328794, 2007).
NID2 also shares sentences with these, for which no sentence is quoted: amoebiasis (1 paper); amyotrophic lateral sclerosis (1); Cerebral ischemia (1); chordoma (1); colon adenocarcinoma (1); colon carcinoma (1); cyst (1); diabetes (1); diffuse large B-cell lymphoma (1); epilepsy (1); fibrosis (1); infection (1); kidney cancer (1); language disorder (1); lung adenocarcinoma (1); mammary adenocarcinoma (1); nasopharyngeal carcinoma (1); neuroblastoma (1); neurodegenerative disease (1); Oral squamous cell carcinoma (1); Parkinson disease (1); prostate carcinoma (1); prostate tumors (1); renal clear cell carcinoma (1); rheumatoid arthritis (1); steatosis (1); urothelial cell carcinoma (1).